LRRC56 (leucine rich repeat containing 56)
Description:
Required for the assembly of dynein arms.
Synonyms: FLJ00101; oda8; DKFZp761L1518; DNAAF12; CILD39
Tractability: No criterion of Open Targets' tractability assessment is met for any kind of drug.
Gene: Protein-coding gene on chromosome 11 (536,841 to 554,925, forward strand). Ensembl gene ENSG00000161328.
Subcellular location: Cell projection, cilium
Gene Ontology:
Molecular function: protein binding
Cellular component: cilium
Genetic constraint (gnomAD): Loss-of-function variants: 39 observed, 41.58 expected, observed/expected ratio (o/e) 0.94, 90% interval 0.73 to 1.23. The synonymous counts are far from expectation, so gnomAD's model fits this gene poorly and the ratio says little. Missense variants: 756 observed, 659.24 expected, observed/expected ratio (o/e) 1.15, 90% interval 1.08 to 1.22. Synonymous variants: 387 observed, 303.34 expected, observed/expected ratio (o/e) 1.28, 90% interval 1.17 to 1.39.
Gene-disease validity (ClinGen):
ClinGen rates the evidence that LRRC56 causes each of these diseases.
ciliary dyskinesia, primary, 39 (autosomal recessive): Moderate.
Homologues: Orthologues: macaque LRRC56 (95% identical), chimpanzee LRRC56 (79% identical), dog LRRC56 (69% identical), mouse Lrrc56 (68% identical), rat Lrrc56 (67% identical), pig LRRC56 (66% identical), guinea pig LRRC56 (61% identical), tropical clawed frog lrrc56 (39% identical), zebrafish lrrc56 (31% identical), Drosophila melanogaster CG14185 (18% identical).
Diseases named in the same sentence as LRRC56 in open-access papers:
LRRC56 is named in the same sentence as 15 diseases in open-access papers, as found by Europe PMC text mining. Sharing a sentence is not in itself a finding about the gene and the disease. The quoted sentences say what the papers report.
ciliopathy (5 papers, 2022 to 2025). A genetic disorder of the cellular cilia or the cilia anchoring structures, the basal bodies, or of ciliary function. "Editor's choice:This work defines a conserved role for Lrrc56 in outer dynein arm deployment in vertebrate multiciliated cells and identifies key protein interactions disrupted in ciliopathy-linked variants." (PMID 41229303, 2025). "In our study, Lrrc56−/− mice exhibited hallmark motile ciliopathy phenotypes, including situs abnormalities, asthenoteratozoospermia, hydrocephalus, and impaired mucociliary clearance." (PMID 41477643, 2025). "To investigate the pathogenic mechanisms associated with LRRC56 deficiency, we established a Lrrc56-knockout mouse model that recapitulated multiple cardinal phenotypes characteristic of motile ciliopathies." (PMID 41477643, 2025). "Together, our study provides new mechanistic insight into LRRC56-associated motile ciliopathies and highlights Xenopus as a powerful platform to investigate the function of poorly characterized ciliary genes in vivo." (PMID 40631331, 2025). "In conclusion, this study demonstrates that LRRC56 deficiency causes distinct motile ciliopathy phenotypes in humans and mice, revealing novel roles of LRRC56 in ciliary function and assembly." (PMID 41477643, 2025). "Next-generation sequencing of known or potential ciliopathy genes revealed him homozygous for a novel mutation c.494T>C of the LRRC56 gene, thus defining PCD as a potential cause of his features." (PMID 36176820, 2022). "To test whether ciliopathy alleles alter compartment-specific distribution, we generated the equivalent alleles in Xenopus Lrrc56 and expressed them in MCCs." (PMID 40631331, 2025). "This work revealed how LRRC56 is transported and unveiled an unexpected link with the dynein docking complex, which might explain some phenotypes in ciliopathy patients with LRRC56 mutations." (PMID 38865178, 2024). "Importantly, ciliopathy-associated alleles in LRRC56 disrupt its normal subcellular localization." (PMID 40631331, 2025). "Lrrc56-knockout mice recapitulated the patient’s laterality defects and also exhibited additional phenotypes consistent with motile ciliopathies, including male infertility, hydrocephalus, and defective mucociliary clearance." (PMID 41477643, 2025). "Human LRRC56, ODAD3, and ODAD1 models were also generated and show similar structures/folding as well as localization of ciliopathy associated alleles." (PMID 40631331, 2025). "Our findings establish LRRC56 as an essential regulator of ciliary motility and highlight its role in the pathogenesis of motile ciliopathies." (PMID 41477643, 2025). "The ciliopathy-associated alleles L136P and L161P mapped to the core LRR domain of Lrrc56, positioned immediately adjacent to the predicted Odad3 interaction surface." (PMID 40631331, 2025). "Human LRRC56, ODAD3 and ODAD1 models were also generated and showed similar structures/folding, as well as localization of ciliopathy-associated alleles." (PMID 41229303, 2025). "Approximately 30% of Lrrc56−/− mice developed hydrocephalus, whereas no hydrocephalus was observed in the patient with biallelic LRRC56 variants, highlighting species-specific differences and incomplete penetrance of motile-ciliopathy phenotypes." (PMID 41477643, 2025).
situs inversus (3 papers, 2023 to 2025). A congenital condition in which there is complete right-to-left reversal of the position of the major thoracic and abdominal organs (that is, they are arranged in a mirror image of the normal positioning). "Previous reports described a homozygous c.494T>C mutation in LRRC56 associated with situs inversus and severe congenital cardiac defects requiring extensive surgical intervention." (PMID 41477643, 2025). "The consequences of situs inversus induced by LRRC56 deficiency are relatively mild." (PMID 39912490, 2025). "Among the surviving LRRC56−/− mice, the most prominent phenotypes included hydrocephalus, situs inversus, male infertility, and bronchiectasis." (PMID 39912490, 2025). "A total of 36% of situs inversus cases in our study were associated with the following genes: DNAH5, DNAI1, DNAI2, DNAAF5, and LRRC56." (PMID 37892347, 2023). "We examined 13 LRRC56-knockout mice, six of which presented situs inversus with a frequency of 46%." (PMID 39912490, 2025). "In this study, the CRISPR/Cas-9 mediated the knockout of LRRC56 gene in C57BL/6JGpt mice, which exhibited severe hydrocephalus, situs inversus, male infertility, and a host of morphological and metabolic disorders." (PMID 39912490, 2025).
Hydrocephalus (2 papers, 2025). Hydrocephalus is an active distension of the ventricular system of the brain resulting from inadequate passage of CSF from its point of production within the cerebral ventricles to its point of absorption into the systemic circulation. "Collectively, these findings indicate that LRRC56 deficiency results in a phenotypic spectrum, with hydrocephalus representing a manifestation predominantly observed in murine models." (PMID 41477643, 2025). "Although it was undeniable that the loss of LRRC56 caused hydrocephalus, the severity of hydrocephalus in LRRC56−/− mice appeared to be irregular, ranging from mild to very severe." (PMID 39912490, 2025). "In addition to hydrocephalus, growth retardation was observed in a subset of Lrrc56−/− pups during early postnatal development." (PMID 41477643, 2025).
male infertility (2 papers, 2025). The inability of the male to effect fertilization of an ovum after a specified period of unprotected intercourse. "We provide the evidence linking LRRC56 deficiency to male infertility characterized by immotile spermatozoa, reduced sperm counts, and multiple morphological abnormalities of the flagella." (PMID 41477643, 2025).
primary ciliary dyskinesia (2 papers, 2022 to 2025). A rare, genetically heterogeneous, primarily respiratory disorder characterized by chronic upper and lower respiratory tract disease. "In conclusion, the knockout of the LRRC56 gene in mice leads to a range of conditions consistent with primary ciliary dyskinesia." (PMID 39912490, 2025). "Heterozygous LRRC56+/− mice developed normally, without exhibiting any symptoms of primary ciliary dyskinesia." (PMID 39912490, 2025).
breast carcinoma (1 paper, 2025). "In summary, our results demonstrate that overexpression of LRRC56 promotes breast cancer progression via upregulating IFT88/YAP1-RhoA/ROCKs pathway, reprogramming extracellular matrix, and enhancing epithelial-mesenchymal transition." (PMID 40388100, 2025). "Further, via in-vivo assessments, we demonstrated that downregulation of LRRC56 effectively inhibits the growth of breast cancer xenograft tumors and their metastasis to the lungs." (PMID 40388100, 2025). "However, the role for LRRC56 in breast cancer progression and regulation of IFT88 and associated pathways in metastatic progression of breast cancer has not been defined." (PMID 40388100, 2025).
polycystic kidneys (1 paper, 2025). "Our data indicate that LRRC56 deficiency resulted in the typical symptoms of PCD, but no associated manifestations of primary cilia disorders such as sensory dysplasia or polycystic kidneys were observed." (PMID 39912490, 2025).
sterility (1 paper, 2025). "Hence, we conclude that LRRC56 knockout results in the loss of both IDAs and ODAs, leading to the formation of abnormal spermatozoa structures and ultimately to sterility in male mice." (PMID 39912490, 2025).
cancer (1 paper, 2025). A tumor composed of atypical neoplastic, often pleomorphic cells that invade other tissues. "Collectively, the LRRC protein family exhibits diverse involvement in cancer metastasis, providing a conceptual framework for investigating the potential mechanisms and functional roles of LRRC56 in MBC." (PMID 40388100, 2025). "Via in vitro functional assessments, we found that LRRC56 pivotally influences the proliferative, migratory and invasive capabilities of cancer cells." (PMID 40388100, 2025).
tumor (1 paper, 2025). "RNA was extracted from xenograft tumor tissues, followed by RT-qPCR analysis, which revealed reduced expression of both LRRC56 and IFT88 in the sh-LRRC56 tumors." (PMID 40388100, 2025). "The results showed downregulation of LRRC56 significantly impaired xenograft tumor growth." (PMID 40388100, 2025). "Furthermore, we validated LRRC56 expression in BC tissues, confirming its high expression in tumor samples." (PMID 40388100, 2025). "Despite limited research on LRRC56 in tumor, our work aims to explore its role in BC metastasis." (PMID 40388100, 2025).
LRRC56 also shares sentences with these, for which no sentence is quoted: asthenospermia (1 paper); bronchiectasis (1); Dextrocardia (1); metabolic disorders (1); Situs inversus totalis (1).